PIK3CB (phosphatidylinositol-4,5-bisphosphate 3-kinase catalytic subunit beta)
Diseases named in the same sentence as PIK3CB in open-access papers (continued):
Sharing a sentence is not in itself a finding about the gene and the disease.
asthma (1 paper, 2022). "Methyl rosmarinate (degree, 8; betweenness centrality, 0.02733; closeness centrality, 0.4715) also shared the same targets (STAT3, PIK3CB, MAPK1, ESR1, SYK, and EGFR) and identical asthma-related signaling pathways with caffeic acid." (PMID 35572723, 2022).
atherosclerosis (1 paper, 2024). A disease characterized by the build-up of fatty material and calcium deposition in the arterial wall resulting in partial or complete occlusion of the arterial lumen. "PIK3CB is involved in apoptosis-related signalling cascades, and its high expression promotes apoptotic cell plaque formation, causing atherosclerosis." (PMID 38715092, 2024).
autoimmune disease (1 paper, 2018). A disorder resulting from loss of function or tissue destruction of an organ or multiple organs, arising from humoral or cellular immune responses of the individual to their own tissue constituents. "Other pro-inflammatory genes enriched in MetS-EVs included the phosphatidylinositol 4,5-bisphosphate 3-kinase catalytic subunit beta isoform (PIK3CB) and several members of the ubiquitin-proteasome pathway involved in development of inflammatory and autoimmune diseases." (PMID 30038668, 2018).
bladder cancers (1 paper, 2016). "We found that PI3Kβ associated with N-cadherin and that PIK3CB depletion selectively disrupted N-cadherin cell adhesions in PTEN-mutant bladder carcinoma." (PMID 27863432, 2016). "Local delivery appears to be suitable for tumors with increased PIK3CB expression that are accessible to local administration, such as bladder cancer." (PMID 27863432, 2016).
endometrioid tumor (1 paper, 2017). A benign, borderline, or malignant epithelial tumor of the female reproductive system characterized by the presence of glands and/or cysts lined by neoplastic cells that resemble endometrial cells. "In addition, different roles were found for the two isoforms in this study, as supported by the association of high mRNA levels of PIK3CB, but not PIK3CA, with markers for high proliferation (CCP score and PCNA levels), notably in endometrioid tumors." (PMID 28002804, 2017).
gingival tumor (1 paper, 2023). "In gingival tissue biopsy, we found that the mRNA expression level of KCNQ1, PIK3CA, and PIK3CB in the gingival tumor tissue of the proband was significantly increased." (PMID 37752101, 2023).
head and neck squamous cell carcinoma (1 paper, 2022). A squamous cell carcinoma that arises from any of the following anatomic sites: lip and oral cavity, nasal cavity, paranasal sinuses, pharynx, larynx, and salivary glands. "While PIK3CA mutations are frequent in head and neck squamous cell carcinomas, mutations involving PIK3CB or PIK3C2B are relatively rare." (PMID 36362284, 2022).
liver fibrosis (1 paper, 2024). "The expression levels of various proteins, specifically PIK3CB, AKT, pAKT, HDAC3, HDAC6, MMP9, MMP2, VIM, and α-SMA, which are implicated in hepatocyte degeneration as well as the initiation and progression of liver fibrosis, were analyzed using Western blotting." (PMID 39683581, 2024).
lung squamous cell carcinoma (1 paper, 2018). "PIK3CB gene is frequently mutated or amplified in several cancer types (such as lung squamous cell carcinoma where its rate of mutations can be as high as 18%), which causes abnormalities in cell survival signaling." (PMID 29370181, 2018).
metastatic cancer (1 paper, 2020). A carcinoma which has spread from the original site of growth to another anatomic site. "Analysis of a few patients with metastatic cancer survive exceptionally longer than others under the same treatment identified multiple common mutations of NOTCH2, NF1, FANCD2, PIK3CB and EPHA5 in tumors that responded exceptionally well to treatments." (PMID 32600248, 2020).
migraine (1 paper, 2022). "PIK3CA, PIK3CB, and PIK3CD are important genes involved in cell proliferation, G protein-coupled receptor signal transduction, and cancer gene expression, and they may be related to migraine caused by glial neuron tumors." (PMID 36479181, 2022). "Such active ingredients may influence neuroactive ligand-receptor interaction, calcium signaling pathways, signaling pathways in cancer, cAMP signaling pathways, and PI3K pathways by acting on multiple targets such as PTGS2, PIK3CA, PIK3CB, PIK3CD, F2, and AR to treat migraine." (PMID 36479181, 2022).
oesophageal cancer (1 paper, 2022). "Alterations of the PI3K pathway are frequent in oesophageal cancer: 10% of tumors present with PIK3CA mutations, 23% with PIK3CA amplifications, 10% with PIK3CB amplifications, and 3% with AKT mutations." (PMID 35326673, 2022).
ovarian clear cell cancer (1 paper, 2024). An invasive malignant neoplasm that arises from the ovary and is characterized by a predominance of clear and hobnail malignant epithelial cells. "It will now be of interest to determine whether the same PIK3CB (E1051K) mutation functions in the pathogenesis of ovarian clear cell carcinoma, and for this purpose MTC-22 cells could be an invaluable tool." (PMID 38573494, 2024). "Thus, MTC-22 could be used to investigate mechanisms underlying ovarian clear cell carcinoma, particularly cases with PIK3CB mutations, or to validate new diagnostic and therapeutic approaches for this type of cancer." (PMID 38573494, 2024).
penile carcinoma (1 paper, 2022). "A link between penile carcinomas and PIK3CB mutations has not been delineated, yet by the time of writing." (PMID 36564761, 2022).
psoriasis (1 paper, 2021). An autoimmune condition characterized by red, well-delineated plaques with silvery scales that are usually on the extensor surfaces and scalp. "PIK3CB mRNA expression was 12.2-fold lower in psoriasis lesional skin when compared to healthy control skin (p < 0.001) and 9.9-fold lower in non-lesional psoriasis skin compared with control skin samples (p < 0.001)." (PMID 34884858, 2021).
rectal cancer (1 paper, 2019). A primary or metastatic malignant neoplasm that affects the rectum. "PIK3CB is involved in the phosphoinositide 3-kinase (PI3K) pathway, which is frequently genetically altered in human colon and rectal cancer and has been identified as a potential therapeutic target." (PMID 31446897, 2019).
seminoma (1 paper, 2025). A radiosensitive malignant germ cell tumor found in the testis (especially undescended), and extragonadal sites (anterior mediastinum and pineal gland). "The singleton missense gain of function variant (p.E1051K) identified in PIK3CB was observed in two seminoma samples (TGCT-2 and TGCT-3), where it co-existed with either KIT (p.N822K) or KRAS (p.G12R) mutations." (PMID 41009531, 2025).
thrombosis (1 paper, 2019).
thyroid cancer (1 paper, 2023). "The PI3K/Akt pathway plays an important role in the tumorigenesis of thyroid cancer, and two of the genes we identified in the poorly differentiated carcinoma component, PIK3CA and PIK3CB, belong to this pathway." (PMID 37249797, 2023).
thyroid neoplasms (1 paper, 2012). "Considering thyroid neoplasms, the increased activation of PI3K pathway could be related to mutations and/or amplification of PIK3CA gene and amplification of PIK3CB gene." (PMID 23259526, 2012).
urothelial carcinoma (1 paper, 2016). A malignant neoplasm derived from the transitional epithelium of the urinary tract (urinary bladder, ureter, urethra, or renal pelvis). "Our results support the use of strategies that decrease PIK3CB expression as a treatment for high-risk non-muscle-invasive bladder cancer with PTEN mutation and low E-cad levels, a frequent phenotype in advanced urothelial carcinoma." (PMID 27863432, 2016).
vitiligo (1 paper, 2019). Generalized well circumscribed patches of leukoderma that are generally distributed over symmetric body locations and is due to autoimmune destruction of melanocytes. "Ultimately, we found that the mRNA and protein levels of HIF-1α, F2RL1, and PIK3CB genes were all elevated in the CD8+ T cells in vitiligo." (PMID 31885781, 2019). "In this study, we found that the mRNA and protein expression level of PIK3CB was significantly increased in vitiligo." (PMID 31885781, 2019). "Notably, we found that HIF-1α (p < 0.0001) and PIK3CB (p < 0.0001) were significantly increased in vitiligo." (PMID 31885781, 2019). "HIF-1α and PIK3CB were significantly increased in lesional skin of vitiligo." (PMID 31885781, 2019). "Due to the unambiguous role of PIK3CB in the production of ROS, we hypothesized that oxidative stress may contribute to the cytotoxic functions of CD8+ T cells to initiate vitiligo via PIK3CB." (PMID 31885781, 2019). "In conclusion, HIF-1α, F2RL1, and PIK3CB may act as novel drivers for vitiligo, which are all closely associated with reactive oxygen species and possibly contribute to the activation and/or migration of melanocyte-specific CD8+ T cells in vitiligo." (PMID 31885781, 2019). "The mRNA and protein expression levels of PIK3CB, HIF-1α, and F2RL1 were all elevated in CD8+ T cells from peripheral blood in vitiligo." (PMID 31885781, 2019). "In our study, the expression levels of PIK3CB and HIF-1α were both increased in the patients with vitiligo." (PMID 31885781, 2019). "However, studies regarding the exact mechanisms about the interplay between PIK3CB and HIF-1α in vitiligo still need to be extended." (PMID 31885781, 2019).
cancer (64 papers, 2011 to 2025). A tumor composed of atypical neoplastic, often pleomorphic cells that invade other tissues. "GSK2636771 demonstrated favourable clinical benefit and a manageable safety profile in PTEN-deficient and/or PIK3CB-abnormal cancer patients in a first-in-human clinical study." (PMID 37489050, 2023). "Previously, researchers have revealed that mutation of PIK3CB increased cancer cell proliferation and promote tumorigenic growth." (PMID 35155229, 2022). "This vital function of PIK3CB in PTEN-deficient cancer cells requires its lipid kinase activity suggesting that PTEN-deficient tumors are dependent on p110β signaling." (PMID 31601918, 2019). "Functional characterisation of variants identified from cancer genome sequencing showed malignant transformation due to a rare mutation (A1048V) in the PIK3CB gene." (PMID 30544563, 2018). "So far, two activating mutations in PIK3CB have been characterized, one of which has been discovered in a few cancer types by whole exome sequencing." (PMID 28002804, 2017). "The role of PI3Kβ in cancer is less understood; PIK3CB mutations in cancer appear at lower frequency than those of PIK3CA, but enhanced PI3Kβ expression is sufficient to induce transformation." (PMID 27863432, 2016). "Interestingly, it has previously been observed that PTEN-deficient cancer cells require the lipid kinase activity of PIK3CB for both PIK3 signaling and growth in vitro, which gives additional support for that potential SL interaction." (PMID 37120674, 2023). "Somatic mutations in PIK3CB have been found in diverse cancer lineages." (PMID 36362284, 2022). "PI3Kβ (encoded by PIK3CB) is particularly important in tumours with PTEN loss, a common event in cancers such as prostate cancer, glioblastoma, endometrial cancer and triple‐negative breast cancer (TNBC)." (PMID 40434054, 2025). "In fact, PIK3CB has attracted considerable attention as a selective survival factor for cancer therapy based on its critical role in apoptosis." (PMID 35096262, 2022). "PIK3CB mutations activate PI3K-dependent signaling, increase cancer cell proliferation and promote tumorigenic growth." (PMID 36564761, 2022). "PI3KCB can be activated by Cdc42 and Rac1, and inactivation of PIK3CB can significantly suppress tumor proliferation, metastasis, and invasion in in PTEN-deficient cancers." (PMID 35154449, 2022). "Kinases that were rarely mutated, including MET, PIK3CB, and PDGFRA/PDGFRB, were found to be substantially overexpressed at the protein level in the same cancer types." (PMID 34552204, 2021). "In that study, it was further observed that miR-1287-5p subdues in vitro anchorage-independent cell growth and in vivo cancer growth by targeting PIK3 catalytic subunit beta (PIK3CB)." (PMID 33435156, 2021). "Class I PI3K isoforms are relevant for cancer, i.e., p110α (encoded by the PIK3CA gene), p110β (PIK3CB gene), p110γ (PIK3CG gene), and p110δ (PIK3CD gene)." (PMID 30832253, 2019). "To dissect the role of PIK3CB in cancer cells expressing endogenous p110βE1051K, we utilized two cell lines identified in the COSMIC cell lines project dataset (cancer.sanger.ac.uk,25Table 1), namely, LN-18 and LoVo." (PMID 29279775, 2017). "Consistently, PIK3CB is not frequently mutated in cancer, but appears to play an important role in tumours with loss of the PIP3 phosphatase PTEN in some but not all contexts." (PMID 41258474, 2025). "PIK3CB has gained more attention in recent years for which more studies proved that PTEN-deficient cancers depend on PIK3CB, not PIK3CA 17,18." (PMID 38356702, 2024). "However, among these three kinds of homologous forms, PIK3CB is more important in cancer than the other two." (PMID 35154449, 2022). "Among them, FOS-promoting cell autophagy was upregulated, whereas PI3K (PIK3CA/PIK3CB), which is a key signaling factor in cancer and was found to regulate ABCB1-mediated MDR in our recent study, was downregulated accompanying the remarkable downregulation of ABCB1." (PMID 35459184, 2022).
cancer (continued). "Evidence suggests that PIK3CB is responsible for driving tumorigenesis in the absence of mutations and specifically in the context of cancers that contain wild-type PI3KCA." (PMID 36362284, 2022). "There are three class IA p110 isoforms (α, β, δ) expressed by the genes phosphatidylinositol-4,5-bisphosphate 3-kinase catalytic subunit alpha (PIK3CA), PIK3CB and PIK3CD, respectively, of which PIK3CA is the most frequently mutated in multiple cancer types, including EOC." (PMID 35582310, 2021). "Three different genes, PIK3CA, PIK3CB, and PIK3CD, encode three specific p110 isoforms, p110α, β, and δ, respectively, and activating missense mutations of PIK3CA have been found as oncogenic in a variety of cancers." (PMID 30682771, 2019). "Similarly, two catalytic subunits of the PI3K complex, the catalytic subunit type 3 (PIK3C3) and the catalytic subunit beta (PIK3CB), contribute to cancer growth and metastasis." (PMID 30115852, 2018). "PIK3CB (the gene encoding p110β) promotes cancer cell proliferation and tumorigenesis in the absence of mutations, especially in wild-type PIK3CA and PTEN-deficient cancers." (PMID 29596304, 2018). "PIK3CB and PIK3CD genes are rarely mutated in cancers but are often amplified or over-expressed." (PMID 28420128, 2017). "In cancer, activating PIK3CA mutations are frequent while PIK3CB is mutated less often." (PMID 28002804, 2017). "Specifically, PIK3CB ranked 286th and 291th by MaxMIF with HumanNet and STRINGv10, was hypothesized as a potential oncogene in certain cancers, and has been subsequently demonstrated as an oncogene, although it has not yet been added to the CGC list under this version." (PMID 30250803, 2018). "In addition, the landscape of the somatic mutations of PIK3CB and FGFR3 could be an indication that their inactivation might promote cancer progression." (PMID 28569218, 2017). "PIK3CB and PI3KCD usually exhibit high expression and amplification in clinical cancer samples 13-16." (PMID 38356702, 2024). "This included genes like, PIK3R2, PIK3CA, BIRC2 and ZBTB14 with implications in cancer that were over-expressed with FC above ≥10 in OS-DW in comparison to OS-R; while, expression of WNT5A, PIK3CB, ACVR1, MAPK13 and GBX2 were significantly reduced." (PMID 31690262, 2019). "PIK3CB and RAF1 have been reported to be ERBB signaling pathway regulators and activators in cancer." (PMID 30929404, 2019). "There is previously no transcription factor being reported to regulate PIK3CB expression in cancers or other diseases." (PMID 38356702, 2024). "The ABL1-I418T, PIK3CB-R231H, CHEK2:c.-4C > T, BRCA2-P3292L, ABL1-E459G, PRPF8-G1796R, PHF6-R274Q, WT1-R435X and ATM-C117Y variants were potentially important cancer variants which were not actionable." (PMID 35896598, 2022). "Nevertheless, proteins p100β, p100δ, and p100γ are also capable of inducing oncogenic transformation in their wild-type form, in line with the fact that PIK3CB, PIK3CD, and PIK3CG are generally amplified or overexpressed, but not mutated, in cancer." (PMID 32033478, 2020). "Class IA PI3Ks (PIK3CA, PIK3CB, and PIK3CD) are the most important isoforms in cancer." (PMID 29642462, 2018). "In addition, CCNE2, PIK3CB, ITGAV, RB1, and BIRC2 involved in cancer pathway were also affected." (PMID 28567416, 2017).